ZNF879 (zinc finger protein 879)
Description:
May be involved in transcriptional regulation.
Synonyms: DKFZp686E2433
Tractability: PROTAC: ubiquitination databases record sites on it.
Gene: Protein-coding gene on chromosome 5 (179,023,804 to 179,035,064, forward strand). Ensembl gene ENSG00000234284.
Subcellular location: Nucleus
Subcellular location (Human Protein Atlas): Nucleoplasm
Gene Ontology:
Molecular function: DNA-binding transcription factor activity, RNA polymerase II-specific; RNA polymerase II cis-regulatory region sequence-specific DNA binding
Biological process: regulation of transcription by RNA polymerase II; regulation of DNA-templated transcription
Cellular component: nucleus; nuclear lumen
Genetic constraint (gnomAD): Loss-of-function variants: 32 observed, 42.14 expected, observed/expected ratio (o/e) 0.76, 90% interval 0.57 to 1.02. The upper end of that interval is the gene's LOEUF score, 1.02, which puts it in group 4 of 6, group 1 being the genes least tolerant of losing a copy. Missense variants: 618 observed, 642.83 expected, observed/expected ratio (o/e) 0.96, 90% interval 0.9 to 1.03. Synonymous variants: 233 observed, 223.55 expected, observed/expected ratio (o/e) 1.04, 90% interval 0.94 to 1.16.
Homologues: Orthologues: chimpanzee ZNF879 (98% identical), dog ZNF879 (91% identical), pig ZNF879 (90% identical), rat Zfp879 (82% identical), guinea pig ZNF879 (81% identical), mouse Zfp879 (81% identical). Paralogues in human: ZNF7 (49% identical), ZNF354B (49% identical), ZNF724 (49% identical), ZNF471 (49% identical), ZNF354A (48% identical), ZNF429 (48% identical), ZNF726 (48% identical), ZNF227 (48% identical), ZNF595 (48% identical), ZNF708 (48% identical), ZNF568 (48% identical), ZNF33B (48% identical), and 164 more.
Diseases named in the same sentence as ZNF879 in open-access papers:
ZNF879 is named in the same sentence as 1 disease in open-access papers, as found by Europe PMC text mining. Sharing a sentence is not in itself a finding about the gene and the disease.
ZNF879 shares sentences with these, for which no sentence is quoted: cancer (1 paper).